FKBP5 (FKBP prolyl isomerase 5)
Diseases named in the same sentence as FKBP5 in open-access papers (continued):
Sharing a sentence is not in itself a finding about the gene and the disease.
endometritis (3 papers, 2024 to 2025). An acute or chronic, usually bacterial infectious process affecting the endometrium. "Gene expression levels were considerably higher in endometritis-affected buffaloes than in resistant ones for the genes A2M, TLR2, IRAK3, CCl2, FCAMR, iNOS, ADAMTS20, KCNT2, MAP3K4, MAPK14, FKBP5, and EPHA4." (PMID 38459095, 2024).
Huntington disease (3 papers, 2023 to 2026). Huntington disease (HD) is a rare neurodegenerative disorder of the central nervous system characterized by unwanted choreatic movements, behavioral and psychiatric disturbances and dementia. "In animal models of Huntington disease, reduction of FKBP5 expression increased LC3-II levels and autophagic flux." (PMID 37452039, 2023). "FKBP5 regulates the degradation of HTT through direct physical interaction, thereby influencing the progression of Huntington’s disease (HD)." (PMID 41602154, 2026).
ischemic stroke (3 papers, 2020 to 2025). A stroke disorder caused by obstruction of blood flow to the brain, due to thrombotic (local blood clot formation) or embolic (due to a blood clot or other material traveling from another site) event. "In this study, we observed significant upregulation of FKBP5 in ischemic stroke patients, which was associated with increased expression of NET markers, such as H3cit and MPO-DNA complexes." (PMID 41098728, 2025). "Further prospective research is needed to verify the potential of FKBP5 as therapeutic targets for ischemic stroke treatment." (PMID 41098728, 2025). "Our study observed the upregulation of FKBP5 in patients with ischemic stroke using transcriptome sequencing." (PMID 41098728, 2025). "A total of 40 ischemic stroke patients and 40 age- and sex-matched healthy donors (HDs) were enrolled in this work to evaluate the expression of FKBP5, the formation of neutrophil extracellular trap (NET), and the correlation between NET and stroke." (PMID 41098728, 2025). "Further prospective research and in vivo experiments using FKBP5 knockout models are needed to investigate the potential of FKBP5 as therapeutic targets for ischemic stroke treatment." (PMID 41098728, 2025). "In conclusion, our findings demonstrated that FKBP5 expression increased in ischemic stroke patients for the first time and contributed to the latent regulatory mechanism of I/R injury." (PMID 32760250, 2020). "A ROC curve was used to assess the predictive value of FKBP5 for the diagnosis of ischemic stroke with sensitivity of 0.82 and specificity of 0.80." (PMID 32760250, 2020). "Collectively, this study indicated that FKBP5 might mediate ischemic stroke through regulating microglia polarization." (PMID 41098728, 2025). "This work validated our hypothesis that FKBP5 might mediate ischemic stroke through regulating NETs and microglia polarization." (PMID 41098728, 2025). "To determine whether FKBP5 is involved in ischemic stroke, we examined its expression in patients with acute ischemic stroke (AIS)." (PMID 32760250, 2020). "To demonstrate this hypothesis, we first examined the pathological role of NETs in ischemic stroke through clinical cases and in vivo experiments, followed by in vitro investigations into FKBP5’s effects on NETs and microglial polarization along with the underlying mechanisms involved." (PMID 41098728, 2025). "However, whether FKBP5 regulates microglial polarization to influence ischemic stroke remains unknown." (PMID 41098728, 2025). "Thus, in this work, we hypothesized that FKBP5 might mediate ischemic stroke through regulating NETs and microglia polarization." (PMID 41098728, 2025). "In addition, our current findings are exclusively derived from in vitro cellular models examining FKBP5’s mechanistic role in ischemic stroke, necessitating further validation through the development of FKBP5-knockdown mouse models to substantiate these conclusions." (PMID 41098728, 2025).
malaria (3 papers, 2023 to 2025). Malaria is a serious and sometimes fatal disease caused by a parasite that commonly infects a certain type of mosquito which feeds on humans. "Induction of both GILZ and FKBP5 by GCs was significantly reduced in patients with clinical malaria compared to AC and in malaria-infected mice compared to uninfected controls." (PMID 37492570, 2023). "Additionally, FKBP5, another highly rhythmic candidate in mammals, influences the host immune system and cerebral manifestations of malaria in mice." (PMID 37638001, 2023). "IL1R2 and FKBP5 have not been previously associated with malaria." (PMID 40383794, 2025). "GC responsiveness, reflected by the FKBP5 fold induction, did not correlate with the expression of GRα, which suggests that reduced GRα expression is not causing the GC insensitivity in PBMCs from patients with clinical malaria." (PMID 37492570, 2023). "Induction of FKBP5 by the GR might thus reduce GC sensitivity in patients with clinical malaria." (PMID 37492570, 2023). "Our results show that circulatory cortisol levels indeed increased in patients with clinical malaria but that sensitivity of patient PBMCs to ex vivo hydrocortisone is reduced, since the induction of GILZ and FKBP5 mRNA and cAMP responses were impaired." (PMID 37492570, 2023).
Sleep disturbance (3 papers, 2023 to 2024). An abnormal pattern in the quality, quantity, or characteristics of sleep. "The present study examined the interaction between FKBP5 gene polymorphisms and job stress on sleep disturbances in a sample of Chinese workers." (PMID 36743961, 2023). "Perhaps the association of FKBP5 variants with sleep disorder was related to the biological role of FKBP5 in HPA-axis functioning within the neuroendocrine system." (PMID 37274192, 2023). "The pleiotropic effect of FKBP5 variants on sleep disorders is worth exploring because of its important biological functions." (PMID 37274192, 2023). "However, the FKBP5 rs9470080-T allele was a protective factor against sleep disturbances, with an OR (95% CI) of 0.65 [0.51–0.83]." (PMID 38525273, 2024). "However, the FKBP5 rs9470080-T allele was a protective factor against sleep disturbances, with an OR (95% CI) of 0.65 [0.51–0.83] (P = 0.001, Bonferroni-corrected P < 0.01)." (PMID 38525273, 2024). "However, the FKBP5 rs9470080-T allele was a protective factor against sleep disturbances." (PMID 38525273, 2024). "FKBP5 variants may be a potential predisposing factor for sleep disorders, especially in REM sleep." (PMID 37274192, 2023). "(b) FKBP5 rs1360780-T and rs4713916-A alleles and the CRHR1 rs110402-G allele were associated with the risk of sleep disturbances." (PMID 38525273, 2024). "The FKBP5 rs1360780-T and rs4713916-A alleles and the CRHR1 rs110402-G allele were risk factors for sleep disturbances, with adjusted ORs (95% CIs) of 1.75 [1.38–2.22], 1.68 [1.30–2.18] and 1.43 [1.09–1.87], respectively (all P = 0.001, Bonferroni-corrected P < 0.01)." (PMID 38525273, 2024). "However, the FKBP5 rs9470080-TT genotype was a protective factor against sleep disturbances, with an adjusted OR (95% CI) of 0.51 [0.28–0.92] (P = 0.001, Bonferroni-corrected P < 0.01)." (PMID 38525273, 2024). "Indeed, a recent study provided evidence that FKBP5 mediates the associations among the HPA axis, GR and the development of sleep disturbance (Buckley, Duggal & Schatzberg, 2008)." (PMID 36743961, 2023).
Stroke (3 papers, 2020 to 2025). Sudden impairment of blood flow to a part of the brain due to occlusion or rupture of an artery to the brain. "Mechanistically, unbiased snRNA-seq analysis shows that the Hippo signaling pathway is altered in Fkbp5 cKO stroke-VAM." (PMID 41355597, 2025). "Further in vitro experiments demonstrated the promotion impact of FKBP5 on NET formation, indicating the potential function of FKBP5 in stroke through regulation NET." (PMID 41098728, 2025). "The results showed that FKBP5 level was significantly elevated in the stroke group compared to the sham group, and the expression significantly decreased in the stroke+CI group." (PMID 41098728, 2025). "Expanded clinical samples further confirmed the high expression of FKBP5 in stroke patients." (PMID 41098728, 2025). "Single-nucleus RNA sequencing (snRNA-seq) analysis of Cx3cr1Cre Fkbp5flox/flox (Fkbp5 cKO) mice in the ipsilateral hemisphere reveals enhanced interactions between stroke-VAM and endothelial cells, influencing signaling pathways that maintain BBB integrity and promote neovascularization." (PMID 41355597, 2025). "Furthermore, the level of FKBP5 increased with the growing National Institute of Health Stroke Scale (NIHSS) score (R2 = 0.5162, P < 0.05)." (PMID 32760250, 2020). "It is found that Fkbp5 acts as a central regulator driving BBB disruption and impaired neovascularization through stroke-VAM." (PMID 41355597, 2025). "FKBP5 and CCL5 modulate p38 MAPK signaling and NET formation, contributing to post-stroke neuroinflammation and neuronal apoptosis." (PMID 41098728, 2025). "The current findings suggest that FKBP5 might modulate CCL5-mediate p38 MAPK signaling and NET formation, thereby contributing to post-stroke neuroinflammation and neuronal apoptosis." (PMID 41098728, 2025).
acute myeloid leukemia (2 papers, 2013 to 2014). Acute myeloid leukemia (AML) is a group of neoplasms arising from precursor cells committed to the myeloid cell-line differentiation. "FKBP5 SNPs have already been implicated in regulating treatment response in cancer, such as acute myeloid leukemia." (PMID 23936393, 2013).
alcohol dependence (2 papers, 2016 to 2024). Physical and psychological dependence on alcohol. "In these conditions, brain regions with high FKBP5 expression, such as the hippocampus, amygdala, dorsal raphe, and locus coeruleus, are implicated in both stress response and alcohol dependence." (PMID 39484582, 2024). "Brain regions with high expression of Fkbp5 have been implicated in both the stress response and the development of alcohol dependence." (PMID 27527158, 2016). "Genetic variations of FKBP5 are associated with an increased risk for depression, PTSD and bipolar disorder and are also associated with a greater risk for comorbid alcohol dependence and PTSD onset." (PMID 27527158, 2016). "The current study has established the foundation for future studies investigating the potential role of FKBP5 in responses to acute and chronic drinking, alcohol withdrawal symptoms and the interplay of stress and Fkbp5 expression on the development of alcohol dependence." (PMID 27527158, 2016).
central obesity (2 papers, 2020 to 2022). "We found a significant relationship between FKBP5 methylation and measures of central obesity (WC), cardiorespiratory fitness (VO2peak) and hyperlipidaemia (LDL levels), which are important determinants of metabolic health." (PMID 35817784, 2022). "Methylation of GR and FKBP5 were analysed in GSAT and ASAT biopsies as representatives of lower body and central obesity, respectively." (PMID 32958048, 2020).
influenza (2 papers, 2020 to 2024). An acute viral infection of the respiratory tract, occurring in isolated cases, in epidemics, or in pandemics; it is caused by serologically different strains of viruses (influenzaviruses) designated A, B, and C, has a 3-day incubation period, and usually lasts for 3 to 10 days. "Taken together, FKBP5 is a novel anti-influenza host factor that restricts IAV infection by the activation of RIG-I-mediated NF-κB signaling." (PMID 32580383, 2020). "FKBP5 is an anti-influenza host factor, and it plays several roles in immunoregulation." (PMID 39795948, 2024). "Our study suggests that FKBP5 is a novel anti-influenza gene." (PMID 32580383, 2020).
ischemia (2 papers, 2020 to 2025). A hypoperfusion of the BLOOD through an organ or tissue caused by a PATHOLOGIC CONSTRICTION or obstruction of its BLOOD VESSELS, or an absence of BLOOD CIRCULATION. "In the present study, FKBP5 was verified upregulated in cerebral I/R injury, related to the severity of ischemia and reperfusion injury." (PMID 32760250, 2020). "In addition, miR-29a-5p agomir treatment suppressed the increasing expression of GSK3β, FKBP5, and AQP4 in the peri-infarction tissue compared with the ischemia-reperfusion group (p < 0.001), as shown by Western blot analysis." (PMID 40529227, 2025).
leiomyoma (2 papers, 2025). A well-circumscribed benign smooth muscle neoplasm characterized by the presence of spindle cells with cigar-shaped nuclei, interlacing fascicles, and a whorled pattern. "These analyses confirmed the leiomyoma-associated dysfunctional regulation of GR transcriptional activity following FKBP5 silencing, affecting both DEX-induced and DEX-suppressed genes." (PMID 40290045, 2025). "DEX-treatment reduced LAMA2 and increased CNN1 levels (coding for extracellular matrix and smooth muscle proteins, respectively) in FKBP5-silenced vs scramble siRNA-transfected leiomyoma cultures." (PMID 40290045, 2025). "Primary cultured leiomyoma cells were transfected with scramble (control) siRNA vs FKBP5 siRNA for 48 hours, then treated with either vehicle or 10−7 M DEX for 24 hours, followed by analysis of RNA by whole-genome RNA-seq." (PMID 40290045, 2025). "RNA-sequencing was performed in leiomyoma cell cultures transfected with scramble or FKBP5-siRNA for 48 hours, then treated with vehicle or dexamethasone (DEX) for 24 hours." (PMID 40290045, 2025). "However, in FKBP5 siRNA-transfected leiomyoma cells, DEX treatment produced a lesser (2.5-fold) increase in HSD11B1 levels compared to control (P < .05)." (PMID 40290045, 2025). "FKBP5, a co-chaperone in glucocorticoid and androgen receptor signaling, was reported highly expressed in fibroids and may regulate genes involved in proliferation and apoptosis in leiomyoma cells." (PMID 40474053, 2025). "In our leiomyoma cell culture RNA-seq data, HSD11B2 transcript levels were extremely low, representing less than 0.1 fragments per kilobase of transcript per million mapped reads and these levels remained extremely low after FKBP5-silencing." (PMID 40290045, 2025). "Notably, this enhanced HSD11B1 expression in leiomyoma was absent following FKBP5 knockdown, highlighting the interconnectivity between FKBP5 and HSD11B1 in inducing a myofibroblast phenotype." (PMID 40290045, 2025).
mastitis (2 papers, 2013 to 2026). Inflammation of breast tissue during lactation or postpartum due to an obstructed duct or infection. "However, many of the most differentially regulated genes, e.g. ABCG2 and FKBP5, have not, to our knowledge, previously been associated with mastitis." (PMID 23324411, 2013). "Comparing genes that express at a different level and the protein network, we identified three key genes (CDKN1A, FKBP5 and SLC7A5) and pathways that mastitis includes both in clinical and subclinical form." (PMID 42127079, 2026).
nephrotic syndrome (2 papers, 2019 to 2023). A collection of symptoms that include severe edema, proteinuria, and hypoalbuminemia; it is indicative of renal dysfunction. "Recently, one study was published on the potential role of FKBP5 polymorphism (rs4713916) in a small group of pediatric nephrotic syndrome patients showing a higher frequency in patients with a steroid-dependent nephrotic syndrome." (PMID 29549463, 2019).
osteoporosis (2 papers, 2023 to 2025). A condition of reduced bone mass, with decreased cortical thickness and a decrease in the number and size of the trabeculae of cancellous bone (but normal chemical composition), resulting in increased fracture incidence. "To explore the relationship between FKBP5 and senile osteoporosis, we specifically deleted FKBP5 in BMSCs by interbreeding FKBP5flox/flox mice with Prx1‐cre transgenic mice, resulting in FKBP5 conditional knockout (FKBP5 CKO) mice." (PMID 40254776, 2025). "To investigate the role of FKBP5 in ageing and osteoporosis, we first assessed its expression in bone tissues from young and older donors, with young donors aged 18–37 years and older donors aged 66–93 years." (PMID 40254776, 2025). "To explore the therapeutic implications of FKBP5 inhibition in osteoporosis, we administered SAFit2, a selective inhibitor of FKBP5." (PMID 40254776, 2025). "We also assessed FKBP5 expression in BMSCs from osteoporosis patients versus age‐matched healthy controls." (PMID 40254776, 2025). "Given our demonstration of FKBP5's essential role in bone metabolism, we propose that FKBP5 may serve as a valuable biomarker for identifying and managing osteoporosis." (PMID 40254776, 2025). "Furthermore, administration of SAFit2 enhances BMD in a senile osteoporosis model, highlighting FKBP5 as a novel target for osteoporosis treatment." (PMID 40254776, 2025). "Importantly, administration of SAFit2, a selective FKBP5 inhibitor, enhanced bone mineral density in an animal model of senile osteoporosis." (PMID 40254776, 2025). "Recent studies have disclosed that FKBP5 is upregulated in bone marrow mononuclear cells from RA patients, and FKBP5 has a direct positive effect on osteoclast differentiation and may play a role in the development of bone destruction and osteoporosis in RA." (PMID 36941600, 2023). "In our animal model of senile osteoporosis, SAFit2 administration resulted in improved BMD, suggesting that FKBP5 plays a pivotal role in osteoporosis management." (PMID 40254776, 2025). "The results showed a significant inverse correlation between FKBP5 expression and both BMD and CT values for the L1 lumbar spine in osteoporosis patients." (PMID 40254776, 2025). "However, the precise contributions and mechanisms of FKBP5 in senile osteoporosis remain unknown." (PMID 40254776, 2025). "This study aims to investigate whether FKBP5 modulates BMSC osteogenic differentiation and its potential role in senile osteoporosis pathogenesis." (PMID 40254776, 2025).
papillary thyroid carcinoma (2 papers, 2022). "Considering recent evidence, Fkbp5, which interacts with heat shock protein 90, can accelerate the progression of papillary thyroid carcinoma." (PMID 35897811, 2022).
Paranoia (2 papers, 2016 to 2018). The feeling and belief that one is being targeted or is a focus of negative or untoward actions, overt or covert, from others. "All the significant bullying x FKBP5 interactions remained, and the association between situational stress and paranoia became significantly moderated by the bullying x FKBP5 interaction." (PMID 27389186, 2016). "The interaction of bullying and the FKBP5 haplotype was significantly associated with PLEs, paranoia, and negative affect." (PMID 27389186, 2016). "We predicted that the interaction between bullying and the CAT risk haplotype of the FKBP5 gene would be associated with higher levels of PLEs, paranoia, and negative affect, but not negative-like symptoms." (PMID 27389186, 2016). "The interaction between bullying and the FKBP5 haplotype was associated with positive, but not negative, psychotic-like experiences, paranoia, and negative affect." (PMID 27389186, 2016). "The results indicated that the interaction between bullying and the risk FKBP5 haplotype was associated with PLEs, paranoia, and negative affect, and that it moderated psychotic-like and affective reactivity to a social stress appraisal (i.e., feeling unwanted by others) in a nonclinical sample." (PMID 27389186, 2016). "Cross-level interaction analyses examined whether bullying, the FKBP5 haplotype, and their interaction moderated the association of social contact and stress appraisals with PLEs, paranoia, and negative affect in daily life." (PMID 27389186, 2016).
polycystic ovary syndrome (2 papers, 2022 to 2023). A disorder that manifests as multiple cysts on the ovaries. "Additionally, since androgens and androgen receptors (ARs) directly and indirectly regulate the FKBP5 gene, this gene may also be associated with polycystic ovary syndrome (PCOS) and hyperandrogenism." (PMID 37398599, 2023).